HDAC1 (histone deacetylase 1)
Diseases named in the same sentence as HDAC1 in open-access papers (continued):
Sharing a sentence is not in itself a finding about the gene and the disease.
head and neck cancer (4 papers, 2015 to 2022). A primary or metastatic malignant neoplasm affecting the head and neck. "CerS1, which generates C18 ceramide, was found to be inhibited in head and neck cancer cells through histone deacetylase 1 (HDAC1) and mi-R-574-5p." (PMID 34071409, 2021). "In our study, we also observed significantly higher levels of HDAC1 in primary tumors from head and neck cancer patients as compared to surrounding normal tissue." (PMID 26000099, 2015). "In this report, we demonstrate that the expression of HDAC1, 2 and 6 is significantly upregulated in head and neck cancer cells." (PMID 26000099, 2015). "In addition, HDAC1, 2 and 6 levels were markedly upregulated in head and neck cancer cell lines." (PMID 26000099, 2015). "We next examined HDAC1, HDAC2 and HDAC6 levels in 8 head and neck cancer cell lines and normal human oral keratinocytes (HOK)." (PMID 26000099, 2015). "We measured HDAC1, HDAC2 and HDAC6 levels in 20 frozen tissue samples from head and neck cancer patients (10 tumor and 10 adjacent normal controls) by real-time PCR." (PMID 26000099, 2015).
Hyperglycemia (4 papers, 2020 to 2023). An increased concentration of glucose in the blood. "They suggested that under the influence of hyperglycaemia, HDAC1 interacts with Atg3 to downregulate autophagy markers, such as LC3-I and LC3-II." (PMID 36864020, 2023). "Next, we employed the role of vaccarin in regulating endothelial cells miR-570-3p and HDAC1 under hyperglycemia conditions in vitro." (PMID 36120375, 2022).
neuropathy (4 papers, 2023 to 2025). A disorder affecting the nervous system that manifests with pain, tingling, numbness, and/or muscle weakness. "In the literature, terpene derivatives have been found to reduce neuroinflammation through HDAC-1 inhibition in a mouse neuropathy model." (PMID 38813490, 2023). "Here, we investigated whether COR167 activity may be related to the modulation of HDAC1 both in the spinal cord of mice with neuropathy and in an in vitro model of neuroinflammation in microglial BV2 cells." (PMID 37371642, 2023). "Moreover, non-psychotropic Cannabis sativa L. oil attenuated peripheral neuropathy symptoms in a mouse model through the modulation of CB2 and the reduction of neuropathy-induced HDAC1 overexpression." (PMID 37371642, 2023).
oligodendroglioma (4 papers, 2016 to 2026). A well-differentiated (WHO grade II), diffusely infiltrating neuroglial tumor, typically located in the cerebral hemispheres. "Patients of oligodendrogliomas with high HDAC1 expression formed a metabolically distinct group, with significantly reduced GPC/PChol ratios, from patients with unchanged HDAC1 expression." (PMID 27011205, 2016).
pancreatic adenocarcinoma (4 papers, 2009 to 2020). "Moreover, a recent study showed that the expression levels of HDAC1, 2, 4, and 6 were associated with clinicopathological parameters of pancreatic adenocarcinoma patients, including the tumor proliferative capacity and patient survival." (PMID 31142371, 2019). "Using the GSE15471 and TCGA-Pancreatic adenocarcinoma (PAAD) datasets, we analyzed the clinical importance of TOP2A-associated genes (HDAC1, HDAC2, HMGB1, HMGB2, NFYA, NFYB, NFYC, and SP1)." (PMID 32977589, 2020). "A study of 29 patients with pancreatic adenocarcinoma and nine patients with chronic pancreatitis showed that the expression levels of HDAC1, 2, 4, and 7 were significantly increased in the former group." (PMID 31142371, 2019). "HDAC-1, −2, −4 and −6 protein expression was assessed immunohistochemically on 70 pancreatic adenocarcinoma tissue specimens and was statistically analyzed with clinicopathological characteristics and patients’ survival." (PMID 26502922, 2015). "High HDAC-1 expression was also more frequently observed in pancreatic adenocarcinoma patients presenting smaller tumor size and earlier histopathological stage, at a non significant level though (p = 0.1544 and p = 0.1127, respectively)." (PMID 26502922, 2015). "Concerning pancreatic adenocarcinoma, only one study conducted on 55 cases has currently evaluated the clinical significance of HDAC-1 member." (PMID 26502922, 2015). "Kaplan-Meier survival curves indicated that pancreatic adenocarcinoma patients presenting concomitant high HDAC-1/HDAC-2 expression had significantly longer survival times compared to those with low expression (log-rank test, p = 0.0255)." (PMID 26502922, 2015). "In view of above considerations, the present study assessed for the first time the clinical significance of HDAC-1, −2, −4 and −6 expression in pancreatic adenocarcinoma." (PMID 26502922, 2015). "The present study aimed to evaluate the clinical significance of HDAC-1, −2, −4 and −6 protein expression in pancreatic adenocarcinoma." (PMID 26502922, 2015). "Kaplan-Meier survival curves indicated that pancreatic adenocarcinoma patients presenting high HDAC-1 expression had significantly longer survival times compared to those with low expression (log-rank test, p = 0.0022)." (PMID 26502922, 2015). "Pancreatic adenocarcinoma displayed strong nuclear immunoreactivity for HDAC1 (32%), HDAC2 (63%), HDAC3 (79%) and RelA/p65 (45%) in a considerable number of cases." (PMID 19912635, 2009). "High HDAC-1 expression was noted in 28 (40.0 %) out of 70 pancreatic adenocarcinoma cases." (PMID 26502922, 2015). "Forty-five (64.3 %) out of 70 pancreatic adenocarcinoma cases were found HDAC-1 positive." (PMID 26502922, 2015). "Pancreatic adenocarcinoma patients with enhanced HDAC-1 and −6 expression showed significantly longer survival times compared to those with low expression (p = 0.0022 and p = 0.0113, respectively), while a borderline association concerning HDAC-2 expression was noted (p = 0.0634)." (PMID 26502922, 2015). "However, the available data so far, evaluating the immunohistochemical expression of HDACs in pancreatic adenocarcinoma remain scarce, being only restricted to HDAC-1 member." (PMID 26502922, 2015). "High HDAC-1 expression was borderline more frequently observed in pancreatic adenocarcinoma patients with absence of lymph node metastases (p = 0.0632)." (PMID 26502922, 2015).
periodontitis (4 papers, 2017 to 2022). An acute or chronic inflammatory process that affects the tissues that surround and support the teeth. "In a recent study, it was found that periodontitis gingival tissue had an increase in mRNA expression of HDAC1, 5, 8, and 9, of these HDAC1 was found in a significantly larger amount in diseased tissue compared to non-diseased tissue." (PMID 29201597, 2017). "The therapeutic effects of HDACi in P. gingivalis-induced periodontitis in mice are dependent on their selectivity: 1179.4b, which targets both class I and class II HDACs, was more potent in suppressing bone destruction than the class I-selective MS-275 (which preferentially targets HDAC1)." (PMID 33256844, 2020). "Moreover, immunohistochemical staining demonstrated expression of HDAC1 by CD3- and TNF-α positive cells, indicating that such cells may be important additional targets to suppress inflammation, suggesting that HDACs modification may be involved in periodontitis pathogenesis." (PMID 36291079, 2022).
pulmonary arterial hypertension (4 papers, 2021 to 2023). Pulmonary arterial hypertension (PAH) is a group of diseases characterized by mean pulmonary artery pressure >20 mmHg and elevated pulmonary arterial resistance leading to right heart failure. "It has been found that up-regulation of histone deacetylases 1 (HDAC1) is involved in the development of pulmonary arterial hypertension (PAH)." (PMID 34465322, 2021). "In samples from patients with pulmonary arterial hypertension (PAH), HDAC1 and HDAC8 were observed to be increased." (PMID 38255639, 2023). "According to previous studies, the HDAC1 expression levels were elevated in the lungs of patients with idiopathic pulmonary arterial hypertension and rats exposed to hypoxia, and HDAC inhibitors prevented hypoxia-induced pulmonary hypertension." (PMID 36899956, 2023).
renal carcinoma (4 papers, 2021 to 2025). A carcinoma arising from the epithelium of the renal parenchyma or the renal pelvis. "In renal carcinoma, CBX4 interacts with histone deacetylase 1 (HDAC1) to suppress the transcriptional activity of the Kruppel-like factor 6 (KLF6) promoter, leading to reduced KLF6 expression and tumor-promoting effects." (PMID 41502529, 2025). "Histone deacetylases class 1 (HDAC1, HDAC2, HDAC3, and HDAC8) are expressed ubiquitously in almost all types of cancer except renal cancer." (PMID 37345150, 2023). "Recent studies showed that HDAC1 and HDAC2 are required for the growth and survival of renal carcinoma cells." (PMID 33398599, 2021). "In human renal cancer cells, KBH-A145 upregulates p21 by inhibiting recruitment of HDAC1 to the p21 promoter." (PMID 33398599, 2021). "Our results showed that UHRF1 inhibited TXNIP expression by enslating HDAC1 to the TXNIP promoter and mediating deacetylation of histone H3K9, thus confirming that UHRF1 may promote tumor progression through epigenetic regulation of TXNIP in renal cancer." (PMID 35656341, 2022).
renal fibrosis (4 papers, 2016 to 2025). A final common manifestation of a wide variety of chronic kidney diseases characterized by glomerulosclerosis and tubulointerstitial fibrosis. "Moreover, in diabetic nephropathy models, FL4 modulates endothelial-mesenchymal transition (EndMT), autophagy, and histone deacetylase 1 (HDAC1) expression, processes involved in renal fibrosis and endothelial dysfunction." (PMID 40943543, 2025).
rhabdomyosarcoma (4 papers, 2019 to 2025). A rare aggressive malignant mesenchymal neoplasm arising from skeletal muscle. "The loss of Hdac1 selectively perturbed T cell-specific transcription, in line with previous studies demonstrating the essential function of HDACs to maintain lineage-specific gene expression in rhabdomyosarcoma." (PMID 40175628, 2025). "We previously reported that the nuclear HDACs (HDAC1, HDAC2 and HDAC3) were co-essential in maintaining CR TF circuits in rhabdomyosarcoma." (PMID 41392987, 2025).
skin cancer (4 papers, 2013 to 2023). "By ablating different combinations of Hdac1 and Hdac2 alleles in the epidermis using K5-Cre, we revealed a specific role of HDAC1 in epidermal development and skin cancer." (PMID 24240174, 2013). "Thus, the hyperproliferation and spontaneous tumour development observed in Hdac1Δ/ΔepHdac2Δ/+ep epidermis and in Hdac1-deficient SOS skin tumours indicates a novel role of HDAC1 as a tumour suppressor in the skin." (PMID 24240174, 2013). "In summary, we have discovered a crucial function of HDAC1 in epidermal homeostasis and as a tumour suppressor in skin cancer." (PMID 24240174, 2013). "Given a potential tumour maintaining role of HDAC1/2 through association with p63 in squamous cell carcinoma, HDAC1 and HDAC2 might also be promising targets in skin cancer treatment." (PMID 24240174, 2013). "The study further suggested that SFN and iberin reduced the viability of skin cancer cells (A375, Hs294T, and B16F10) and decreased the expression of HDACs (HDAC1, HDAC2, HDAC4, and HDAC6)." (PMID 36765652, 2023). "We therefore examined the effect of ablation of HDAC1 and HDAC2 in the genetic K5-SOS skin tumour model." (PMID 24240174, 2013). "The mechanistic insights revealed a decreased methylation ratio of CpG dinucleotides in the promoter region of Nrf2 in SFN-treated skin cancer cells, and SFN also attenuated the expression of HDACs (HDAC1, HDAC2, HDAC3, and HDAC4) and DNMTs (DNMT1, DNMT3a, and DNMT3b)." (PMID 36765652, 2023). "Surprisingly, ablation of HDAC1 but not HDAC2 in a skin tumour model leads to accelerated tumour development." (PMID 24240174, 2013).
steatosis (4 papers, 2015 to 2023). Increased lipid within the cytoplasm of cells. "HDAC1 is thought to inhibit liver regeneration in aged mice and liver‐specific overexpression of HDAC1 resulted in steatosis, a marker of liver aging." (PMID 31368626, 2019).
synovial sarcoma (4 papers, 2016 to 2025). "We find that exposure of synovial sarcoma cells to FK228, a potent HDAC1/2 inhibitor, leads to the induction of FYN mRNA and protein expression which could render synovial sarcoma cells resistant to growth inhibition after loss of SS18-SSX function." (PMID 39045458, 2024). "Both, synovial sarcoma and chondrosarcoma cells expressed class I HDACs and protein expression levels for HDAC1, 2, 3, and 8 did not change in response to HDACi treatment." (PMID 29100385, 2017). "Chromatin immunoprecipitation revealed a decrease in HDAC1 and H3K23me3 at the EGR1 promoter, a known target for repression by the SS18-SSX/TLE1/ATF2 complex consistent with a disruption of the biologic effects on SS18-SSX target genes in synovial sarcoma." (PMID 27120803, 2016).
thyroid cancer (4 papers, 2019 to 2024). "HDAC1, a molecule that regulates cell cycle progression and proliferation, has been characterized as a proteomic signature in thyroid cancer and its expression is linked to tumor size and progression." (PMID 38791433, 2024). "By knocking out HDAC1 and HDAC2 using clustered regularly interspaced short palindromic repeats (CRISPR/Cas9), we investigated the impact of HDAC loss and how acetylation is regulated in thyroid cancer cells and observed the downstream signaling pathways and cell cycle regulation." (PMID 30669676, 2019). "Based on the evidence presented in this study, considerable epigenetic alternations, such as HDAC1 and HDAC2, in advanced thyroid cancer were investigated and more epigenetic alterations are being studied." (PMID 30669676, 2019).
type 2 diabetes (4 papers, 2013 to 2022). "Thus, the modulation of HDAC1-PKA-Tph1 signaling in β-cells could serve as a novel therapeutic strategy for the treatment of type 2 diabetes." (PMID 32641996, 2020). "Additionally, we identified HDAC1/PKA signaling as a novel regulatory axis for Tph1 expression, thus providing a potential therapy for type 2 diabetes characterized by impaired β-cell functional compensation." (PMID 32641996, 2020). "While the functional significance of alterations in HDAC1 and HDAC2 needs to be clarified in metabolic disorders, our study unraveled a consistent increase in both HDAC3 activity and HDAC3 transcriptional levels in PBMCs from patients with type 2 diabetes." (PMID 27904654, 2016). "In our study, we observed increased HDAC1 mRNA expression (albeit not statistically significant) in patients with type 2 diabetes." (PMID 27904654, 2016).
acne vulgaris (3 papers, 2022 to 2024). "In a study comprising a cohort of 25 individuals with patchy AA, 26 patients with acne vulgaris, and 25 healthy controls, the enzyme-linked immunosorbent assay (ELISA) data showed a decreased level of histone deacetylase 1 (HDAC1) in both AA and acne vulgaris patients." (PMID 38235133, 2023). "Another histone deacetylase, HDAC1, exhibits dysregulation in patients with AA and acne vulgaris." (PMID 38235133, 2023). "HDAC1 appears to be dysregulated in AA and acne vulgaris individuals." (PMID 35625530, 2022). "The expression of CXCL10, MMP9, IL1B, CXCL8, and CXCR4 were co-regulated by IRF1, STAT1, STAT3, IKBKB, HDAC1, ETS1, and CEBPB, which were highly expressed in rosacea and acne lesions." (PMID 38321132, 2024).
acute kidney injury (3 papers, 2017 to 2020). Sudden and sustained deterioration of the kidney function characterized by decreased glomerular filtration rate, increased serum creatinine or oliguria. "Low HDAC1 expression has been reported in acute kidney injury in vitro, and the unhindered activity of HDAC1 has been regarded as a prerequisite factor for renal protection and regeneration following acute kidney injury." (PMID 32596952, 2020). "As a member of the HDAC superfamily, HDAC1 plays a key role in renal protection and regeneration of acute kidney injury." (PMID 32596952, 2020). "In addition, treatment with romidepsin, a selective inhibitor of HDAC1, significantly attenuated lipopolysaccharide-induced acute kidney injury." (PMID 32848758, 2020). "ATF3 was demonstrated interacted directly with histone deacetylase 1 (HDAC1) and recruited HDAC1 into the ATF/NF-κB sites in the IL-6 and IL-12b gene promoters to protect against acute kidney injury." (PMID 28912732, 2017).
acute leukemia (3 papers, 2016 to 2024). A clonal (malignant) hematopoietic disorder with an acute onset, affecting the bone marrow and the peripheral blood. "Regarding other LSD1 inhibitors, ORY-1001 from Oryzon is in phase I/IIA trial for the treatment of acute leukemia, GSK2879552 is under a phase I clinical trial in patients with AML and SCLC, and 4SC-202, a HDAC1-3 and LSD1 inhibitor ended a phase I trial for hematological malignancies." (PMID 27222667, 2016). "Although a previous study showed that fused NUP98 proteins, i.e., NUP98-HOXA9 and NUP98-PMX1, interact with HDAC1 and are involved in the regulation of genes implicated in acute leukemia, our experiments with transiently expressed NUP98 indicate that unfused NUP98 might not interact with HDAC1." (PMID 38449868, 2024).
acute pancreatitis (3 papers, 2021 to 2024). An acute inflammatory process that leads to necrosis of the pancreatic parenchyma. "Valproic acid is a specific HDAC1 inhibitor, which attenuates proteinuria, fibrosis, and inflammatory effects and even acute pancreatitis." (PMID 34025445, 2021). "The ATF4-mediated histone deacetylase HDAC1 promotes the progression of acute pancreatitis." (PMID 38913045, 2024).
acute promyelocytic leukemia (3 papers, 2012 to 2019). An aggressive form of acute myeloid leukemia (AML), characterized by arrest of leukocyte differentiation at the promyelocyte stage, due to a specific chromosomal translocation t(15;17) in myeloid cells. "This HDAC1 result is in contrast to HL-60 human promyelocytic leukemia cells that are resistant to HDIs, which have been shown to possess significantly higher levels of HDAC1 than parental cells." (PMID 22684370, 2012).
allergic asthma (3 papers, 2022 to 2025). A asthma with a basis in a pathological type I hypersensitivity reaction. "Our work further illustrates that HDAC1 is a master regulator of pTh2 cells, suggesting that therapeutic approaches aimed at inhibiting HDACs in allergic asthma, like the use of SCFAs and synthetic HDAC inhibitors, should be revisited." (PMID 40089475, 2025). "Our work highlights the importance of HDAC1 in HDM-induced allergic asthma and pTh2 cell differentiation." (PMID 40089475, 2025). "To determine the impact of HDAC1 deletion in HDM-induced allergic asthma, we sensitised and challenged WT and HDAC1-cKO mice with HDM." (PMID 40089475, 2025). "Animal models of allergic asthma exhibits significantly higher expression of HDAC1 compared to control." (PMID 36311721, 2022). "Furthermore, we find that HDAC1 is essential to restrict HDM-induced allergic asthma and the differentiation of lung and in vitro generated pTh2 cells." (PMID 40089475, 2025). "Based on our findings, augmenting the activity of HDAC1 might represent an approach to limiting allergic asthma." (PMID 40089475, 2025). "Our findings suggest that HDAC1 may involve in hypoxia induced inflammation in allergic asthma and inhibition of HDAC1 by SOB and CUR reduces inflammation by inhibiting activation of PI3K/Akt axis." (PMID 37316684, 2023). "Along with HDAC1, enhanced expressionof MMP-9, NF-kB and suppressed expression of H3acK9 was observed, which suggested probable relationship between these factors in allergic asthma pathogenesis." (PMID 37316684, 2023). "Here we investigate immune regulation in allergic asthma by single-cell RNA sequencing in mice challenged with house dust mite, in the presence and absence of histone deacetylase 1 (HDAC1) function." (PMID 40089475, 2025).